LINC01128 (long independently transcribed non-coding RNA 1128)
Synonyms: RP11-206L10.11
Gene: Long non-coding RNA gene on chromosome 1 (825,138 to 868,835, forward strand). Ensembl gene ENSG00000228794.
Diseases named in the same sentence as LINC01128 in open-access papers:
LINC01128 is named in the same sentence as 8 diseases in open-access papers, as found by Europe PMC text mining. Sharing a sentence is not in itself a finding about the gene and the disease. The quoted sentences say what the papers report.
acute myeloid leukemia (2 papers, 2022). Acute myeloid leukemia (AML) is a group of neoplasms arising from precursor cells committed to the myeloid cell-line differentiation. "LINC01128 has previously been implicated in cervical cancer and acute myeloid leukemia, however, there have been no reports on its effects in PC." (PMID 35193567, 2022).
breast carcinoma (2 papers, 2021 to 2024). "In addition, LINC01128 was reported in pancreatic adenocarcinoma, breast cancer, and diabetes." (PMID 38796816, 2024). "Only high expression of LINC01128, CCDC18-AS1, SH3BP5-AS1, HOTAIRM1, LINC01140, SGMS1-AS1, LINC01578 or LINC00667 had favorable prognosis in breast cancer." (PMID 34828282, 2021). "Mechanistic exploration revealed that a potential ncRNA-mRNA axis, involving LINC01128/LINC01140/SGMS1-AS1/LINC00667-miR-137/miR-429-BCL2, might be partially responsible for MUC14′s functions in breast cancer." (PMID 34828282, 2021).
cervical cancer (2 papers, 2022). A primary or metastatic malignant neoplasm involving the cervix. "For instance, LINC01128 facilitates cervical cancer by functioning as a sponge of miR-383-5p, thus enhancing the SFN expression and promoting cell proliferation, migration, and invasion." (PMID 35571024, 2022).
tumor (4 papers, 2020 to 2024). "As an independent prognostic factor of CRC, upregulation of LINC01128 predicts poor prognosis and accelerates tumor deterioration through miR-363-3p." (PMID 38796816, 2024). "Using this model, we found that the LINC01128 knockout group (sh‐LINC01128) exhibited significantly less tumour propagation than the sh‐NC group." (PMID 33108067, 2020). "Our experiments also believed that LINC01128 knockdown markedly suppressed the biological function of CRC cells, suggesting that LINC01128 may act as a tumor promoter in CRC." (PMID 38796816, 2024). "Based on our network and the ceRNA mechanism, we speculated that LINC01128 might act as a tumor suppressor in MM through multiple mechanisms, including miR-142-5p/PARP9 or FAM133A axis, and the miR-299-3p/estrogen-related receptor gamma axis." (PMID 33193574, 2020). "Furthermore, LINC01128 promoted tumor growth and regulated LDHA protein expression in vivo." (PMID 35193567, 2022). "Furthermore, silencing LINC01128 significantly inhibited the proliferation, migration, invasion, and epithelial-mesenchymal transition (EMT) of PC cells in vitro and tumor growth in vivo, while LINC01128 overexpression promoted these processes." (PMID 35193567, 2022).
LINC01128 also shares sentences with these, for which no sentence is quoted: cancer (1 paper); diabetes (1); osteosarcoma (1); pancreatic adenocarcinoma (1).